BRCA2 (BRCA2 DNA repair associated)
Diseases named in the same sentence as BRCA2 in open-access papers (continued):
Sharing a sentence is not in itself a finding about the gene and the disease.
breast cancer (continued). "Most older patients with the BRCA1 and BRCA2 pathogenic variants in exons 12-24/25 with luminal breast cancer may gain a similar survival benefit from other risk-reducing strategies or surveillance." (PMID 36580360, 2022). "In addition, 27% of carriers of the BRCA1 pathogenic variant and 19% of carriers of the BRCA2 pathogenic variant will develop a second primary contralateral breast cancer within 10 years after the first primary breast cancer diagnosis." (PMID 36580360, 2022). "PVs in BRCA1 and BRCA2 possess a 50% to 80% lifetime risk of developing breast cancer." (PMID 35323371, 2022). "Furthermore, endogenous or environmental aldehydes were suggested to play a role in genome instability by inducing haploinsufficiency of BRCA2, a breast cancer susceptibility gene." (PMID 35657923, 2022). "However, studies have shown that the combination of BRCA1 and BRCA2 mutations accounts for the most high-risk breast cancer families." (PMID 35740092, 2022). "The tumor-susceptibility gene BRCA2 with high penetrance is primarily concerned with the homologous recombination mechanism of DNA repair, and its variants are the leading causes of familial and early-onset breast cancer." (PMID 35912179, 2022). "Interestingly, all the patients with a germline BRCA1 or BRCA2 mutation and a second malignancy first developed a breast cancer and thereafter an OC." (PMID 36555431, 2022). "In conclusion, this study confirms that, aside from female breast and ovarian cancers, BRCA1/2 PVs are associated with increased risks of breast cancer in men, and pancreatic and stomach cancers in both sexes, and that only BRCA2 carriers are at elevated prostate cancer risk." (PMID 35077220, 2022). "Notably, among young patients diagnosed with breast cancer below the age of 30, approximately 25% of them carried BRCA2 deleterious mutations and 6.2% of them harbored ATM mutations, significantly higher than in women diagnosed ≥ 40 years (P=0.002)." (PMID 35494038, 2022). "Genetic characteristics of the study population: BRCA1 or BRCA2 mutations may be responsible for approximately 10% of ovarian cancer cases and 3–5% of breast cancer cases." (PMID 35950060, 2022). "In addition, prostate cancer patients with a pathogenic germline variant in the BRCA2 gene have a higher risk of developing metastases and dying from prostate cancer at an early age, and they have a higher risk of developing breast cancer." (PMID 36581909, 2022). "Using different risk models for pathogenic BRCA1 and BRCA2, we observed that the predicted risk was higher in breast cancer cases carrying germline loss-of-function variants in BRCA1 and/or BRCA2 than in other breast cancer genes, or those carrying wild-type genes." (PMID 35353237, 2022). "Therefore, clinical guidelines in general discourage from testing for BRCA2 mutations in persons below age 18, given that screening for breast cancer in BRCA2 carriers (e.g. MRI scans of the breast) is generally only offered at age 25 and older." (PMID 36083315, 2022). "Whilst breast cancers arising in patients with BRCA1 or BRCA2 mutation carriers account for less than 5% of breast cancers, if epigenetic alterations, such as BRCA1 methylation are taken into account these make up approximately 15% of all patients and almost half of those with TNBC." (PMID 35158742, 2022). "This has been shown by a recent study which found significantly longer survival free of invasive or distant disease when using olaparib as adjuvant therapy after neoadjuvant or adjuvant chemotherapy and local therapy in early breast cancer patients with BRCA1 or BRCA2 germline pathogenic variant." (PMID 36085046, 2022). "Mutations of BRCA2 have been linked to tumorigenesis in murine sporadic breast cancers." (PMID 35740092, 2022). "Genetic mutations such as mutation of BRCA1 and BRCA2 genes also contribute to breast cancer." (PMID 35454076, 2022). "Germline BRCA1 and BRCA2 loss-of-function variants predispose to development of breast cancer." (PMID 36324133, 2022).
breast cancer (continued). "Measures of clinical validity and utility compare favorably to other genetic risk tests, such as BRCA1 and BRCA2 screening for breast cancer risk and HLA-B*15:02 pharmacogenetic screening for pharmacovigilance of carbamazepine to prevent Stevens-Johnson Syndrome and Toxic Epidermal Necrolysis." (PMID 36588876, 2022). "One of the most famous examples, mutations in BRCA1/BRCA2 genes, have given patients the ability to reliably assess their risk of developing breast cancer in their lifetime, as well as their risk of relapse after a first bout of breast cancer." (PMID 36010859, 2022). "However, pathogenic mutations in BRCA1 and BRCA2 increase the risk of breast cancer by 65% and 45%, respectively." (PMID 35743744, 2022). "Breast cancer cells deficient in BRCA2 were reported to be sensitized to PARG inhibition." (PMID 35163783, 2022). "Notably, BRCA2 mutation has been validated as a genetic target for PARP inhibitors in breast cancer 62, providing treatment hopes for HAS patients with a BRCA2 mutation." (PMID 36147475, 2022). "In parallel with our study, one group has investigated the prevalence of BRCA gene mutation in Saudi women with breast cancer; they found that mutation of BRCA2 gene was found in 7 patients out of 310 with total percentage of both BRCA1 and BRCA2 of 12.9%; the percentage of BRCA2 was 2.2%." (PMID 36268271, 2022). "However, there was a doubling in the risk of diabetes among BRCA1 or BRCA2 mutation carriers in the 15-year period after diagnosis of breast cancer." (PMID 35432218, 2022). "Moreover, BRCA1 and BRCA2 mutation is seen in 80-90% of single gene familial breast cancers and about 3-6% of all breast cancers." (PMID 36705103, 2022). "Six different germline mutations in breast cancer families are likely to be due to BRCA2." (PMID 35563727, 2022). "Predicted loss of function variants in BRCA1 and BRCA2 were present at increased frequencies in individuals with a breast cancer diagnosis and ovary as an additional cancer site, such that 28.6% and 13.6% of individuals, respectively, were a carrier for at least one variant in the burden set." (PMID 36199081, 2022). "Lastly, we found that BRCA2 isoform switching may be a pro-tumorigenic event that appears in both breast and ovarian recurrences and is associated with reduced breast cancer patient survival." (PMID 36344544, 2022). "A BRCA2 gene mutation is the most important risk factor for the development of male breast cancer." (PMID 35885460, 2022). "The BRCA1 and BRCA2 genes, are best known as breast cancer susceptibility genes." (PMID 35413944, 2022). "The datasets “Phenotypes” and “IlluminaHiSeq Gene Expression RNAseq” were downloaded in order to identify breast cancer patients with mutations affecting BRCA1 or BRCA2 or amplification affecting ErbB2 and the expression data of 20,530 different genes, respectively." (PMID 35740092, 2022). "Mutations in the BRCA1 and BRCA2 genes are known risk factors and drivers of breast cancer." (PMID 36276952, 2022). "According to a study by Gucalp, male breast cancer is almost exclusively hormone receptor positive (+), including androgen receptor (AR), and is associated with a higher prevalence of BRCA2 germline mutations, particularly in men at an increased risk for developing high-risk breast cancer." (PMID 35885460, 2022). "Moreover, pathogenic BRCA2 variants were a predictor of hematological adverse reactions in breast cancer patients during PTX chemotherapy." (PMID 35847868, 2022). "Interestingly, we noted that the impact of RRBSO in patients with the BRCA1 and BRCA2 pathogenic variants with luminal breast cancer in stage I/II increased with the age." (PMID 36580360, 2022).
breast cancer (continued). "BRCA1 or BRCA2 mutation also affects the treatment regimens for breast cancer." (PMID 36518309, 2022). "Similarly, there was report of a cat with mammary carcinoma carrying a pathogenic somatic mutation in exon 11 of BRCA2." (PMID 36288160, 2022). "Our previous studies showed an association between monoallelic BRCA2 germline mutations and dysfunctional telomeres in epithelial mammary cell lines and increased risk of breast cancer diagnosis for women with BRCA2 999del5 germline mutation and short telomeres in blood cells." (PMID 35052422, 2021). "A family history of ovarian cancer—especially those characterized by BRCA1 and BRCA2 mutations—might also induce a greater risk of breast cancer." (PMID 34503097, 2021). "Newer effective personalized therapies, including poly-ADP-ribose polymerase (PARP) inhibitors targeting BRCA1 or BRCA2 pathogenic mutations directly or via their pathways are increasingly available for ovarian and breast cancer patients who are carriers of such variants." (PMID 34072979, 2021). "The PALB2 gene was recently classified as a high risk breast cancer susceptibility gene in Caucasian women, with 53% cumulative risk to age 80 years and 7-fold relative risk for female breast cancer, which was comparable to the breast cancer risk of the BRCA2 gene in Caucasian women." (PMID 34606182, 2021). "Although mutations in BRCA1 and BRCA2 are two of the most widely known genetic determinants of breast and ovarian cancer, they are among many in a series of CPGs implicated in the formation of hereditary breast cancer." (PMID 34070674, 2021). "Similarly, the discovery of Rad52 and its role in HR has opened another option to explore for treating BRCA2-deficient breast cancer cells." (PMID 33916151, 2021). "Approximately 72 and 69% of women who harbor BRCA1 or BRCA2 gene mutations, respectively, are likely to develop breast cancer by the age of 80, equating to a 5–20 fold increased risk of developing breast cancer due to the loss of genetic fidelity in other tumour suppressor genes." (PMID 34209669, 2021). "A veterinary investigation of mammary tumors in dogs found evidence that SNPs in exons 24 and 27 of BRCA2 may be associated with cancer development." (PMID 33503928, 2021). "However, there were more HR+/HER2- breast cancers in BRCA2 mutation-carriers (57.0%) and fewer in BRCA1 mutation-carriers (22.6%) than the non-carriers (40.9%, p=1.4×10-5 and 3.0×10-4, respectively)." (PMID 34336698, 2021). "Recurrent BRCA1 and BRCA2 mutations in breast cancer patients of African ancestry." (PMID 35096615, 2021). "In addition, both retrospective and prospective analyses confirmed that breast cancer risk in men was 7.1% by age 70 years and 8.4% by age 80 years in BRCA2 carriers." (PMID 34356066, 2021). "HR defects, e.g., due to inactivating mutations in BRCA1 and BRCA2 genes, are exploited in ovarian and breast cancer treatment, where single strand repair inhibitors (PARP inhibitors) as post-chemotherapy maintenance treatment show high efficacy in the HR-deficient subpopulation of patients." (PMID 34616682, 2021). "Interestingly, SNORA68 is located at the p13.1 locus on chromosome 19 (19p13.1), a region previously associated with susceptibility to both ovarian and breast cancer in the population with BRCA1 or BRCA2 mutation carriers." (PMID 33125686, 2021). "While BRCA1-associated tumors are most commonly a high-grade invasive ductal carcinoma of no special type and the majority fall into the “basal-like” subtype of breast cancer, the BRCA2-associated tumors are very similar to sporadically occurring “luminal-type” tumors." (PMID 33540843, 2021). "About 10%-15% of breast cancer cases are hereditary, which might be related to the mutations of BRCA1 (Breast cancer susceptibility gene 1) and BRCA2 (Breast cancer susceptibility gene 2)." (PMID 33407485, 2021). "Breast cancer risk for BRCA1/BRCA2 mutation carriers varies depending on other genetic factors." (PMID 33597508, 2021).
breast cancer (continued). "In addition, 5 male breast cancer cases were investigated among which 2 carried BRCA2 mutations (c.1310_1313delAAGA and c.1389_1390delAG)." (PMID 34490083, 2021). "In a landmark study, anti-DNA antibodies were found to be lethal to BRCA2-deficient human cancer cells, suggesting that the presence of lupus autoantibodies may contribute to the decreased risk of breast cancer observed in SLE patients." (PMID 33632283, 2021). "About 20% of HGSOCs harbor germline mutation in breast cancer genes BRCA1 or BRCA2." (PMID 34572778, 2021). "Breast cancer is linked to several distinct life events, such as genetic mutations to the BRCA1 (breast cancer gene 1) and BRCA2 (breast cancer gene 2) genes, high breast density, family history of the disease, late full-term pregnancy, lack of physical activity, and smoking and alcohol consumption." (PMID 34638847, 2021). "Mutations in the BRCA1 or BRCA2 genes induce the progress of breast cancer." (PMID 34710987, 2021). "Specifically, retrospective analyses from the Breast Cancer Linkage Consortium showed a relative risk (RR) of PCa in male BRCA2 and BRCA1 mutation carriers of 4.65 (95% confidence interval (CI): 3.48–6.22) and 1.07 (95% CI 0.75–1.54) respectively, the latter being similar to the general population." (PMID 34830851, 2021). "Regarding BRCA2 variants, twelve patients developed breast cancer." (PMID 34680878, 2021). "Germline pathogenic variants (PVs) in the BRCA1 or BRCA2 genes cause high breast cancer risk." (PMID 33573335, 2021). "A recent study on a large prospective cohort showed that the cumulative breast cancer risk to age 80 years was 72% for BRCA1 and 69% for BRCA2 carriers, and the cumulative risk for contralateral breast cancer 20 years after breast cancer diagnosis was 40% for BRCA1 and 26% for BRCA2 carriers." (PMID 33718150, 2021). "Therefore, patients who carry BRCA2 germline mutations are much susceptible to breast cancer and ovarian cancers." (PMID 33414393, 2021). "Germ-line mutation in BRCA1 or BRCA2 are found in 3–4% of all women with breast cancer." (PMID 33996049, 2021). "Mutations in BRCA1 and BRCA2 are closely related to increased susceptibility to breast cancer." (PMID 34917121, 2021). "And BRCA2 mutation was associated with disease progression in breast cancer." (PMID 33931024, 2021). "Here, we apply a novel strategy using a case-only GWAS design, in which SNP genotype frequencies in 7,257 BRCA1 and 5,097 BRCA2 mutation carrier BC cases are compared to those in 60,212 BC cases from the Breast Cancer Association Consortium (BCAC), unselected for mutation status." (PMID 33597508, 2021). "Consistent with previous reports, germline and, to a lesser extent, somatic BRCA1 mutations were associated with basal breast cancer phenotype-related functional gene sets, while germline and somatic BRCA2 mutations were associated with luminal phenotype-related gene sets." (PMID 33525353, 2021). "Recent data had suggested that patients with advanced-stage breast cancer associated with BRCA1 or BRCA2 mutations may benefit from PARP (poly ADP ribose polymerase) inhibitors like olaparib and talazoparib; both are currently approved for such situation." (PMID 34290354, 2021). "Interestingly, the functional associations were reversed in somatic BRCA2 groups: In breast cancer, they were associated with immune response, while in ovarian cancer these mutations were associated with chromosome organization and maintenance." (PMID 33525353, 2021). "Carriers of germline pathogenic or likely pathogenic variants in BRCA1 or BRCA2 have significantly increased lifetime risks of breast cancer, ovarian cancer, and other cancer types; this phenomenon is known as hereditary breast and ovarian cancer (HBOC) syndrome." (PMID 35087763, 2021). "Interestingly, PCAF levels were found to be reduced in several BRCA-deficient breast cancer cell lines and BRCA2-mutant breast cancer tumors." (PMID 34548613, 2021).
breast cancer (continued). "The ongoing search for additional genes that could be involved in hereditary susceptibility breast cancer families led to the discovery of the BRCA2 gene in 1995." (PMID 34573353, 2021). "The BRCA2 mutation frequency was reported to be 1–3% in breast cancer." (PMID 33662042, 2021). "This reduces the risk of ovarian cancer by up to 95% in carriers of pathogenic variants, may reduce the risk of breast cancer (BRCA2) and reduces breast/ovarian/all-cause mortality." (PMID 33836815, 2021). "Furthermore, it is not accurate for use in the known carriers of pathogenic variants in BRCA1 or BRCA2, or other breast cancer susceptibility genes." (PMID 34771713, 2021). "This paradigm is best exemplified in BRCA1 and BRCA2 pathogenic variant carriers where knowledge of the function of these genes led to the development of poly (ADP-ribose) polymerase (PARP) inhibition as a novel therapy for the treatment of breast cancers." (PMID 34439109, 2021). "According to a large-scale international joint consortium, it was shown that histopathological features of breast cancer refine the likelihood estimation for BRCA1 or BRCA2 variant status, which can be informative for genetic testing and clinical management of the patients involved." (PMID 35008774, 2021). "In order to better assess the genetic risk to develop cancer in this population, we analyzed the coding regions and the exon–intron junctions of the two main breast cancer susceptibility genes, BRCA1 and BRCA2 through next generation sequencing (NGS) in 51 Burkinabe women affected by breast cancer." (PMID 34717758, 2021). "Also, albeit uncommon, either BRCA1 or BRCA2 mutation has been detected in women with NF1 who develop breast cancer." (PMID 33954070, 2021). "This is the case for women with breast cancer that also have the BRCA1 or BRCA2 mutation." (PMID 34575624, 2021). "The risk of breast cancer is elevated in men with a BRCA1 or BRCA2 mutation." (PMID 34461861, 2021). "Variants of unknown/uncertain significance (VUS) in breast cancer susceptibility genes BRCA2, CHEK2 and BRIP1 were also identified in three different PABC patients (15%)." (PMID 34011307, 2021). "How defects in telomere length homeostasis of BRCA2 mutation carriers might be related to consequences of possible telomere RS before and after breast cancer diagnosis needs to be answered in future studies." (PMID 35052422, 2021). "BRCA2 carriers showed positive family history of other cancers, which may indicate that in addition to breast cancer, BRCA2 mutations may increase the risk of developing other cancers including prostate, pancreatic, pharyngeal, brain cancers and leukemia." (PMID 34206661, 2021). "BRCA1 or BRCA2 are recurrently mutated in cancers of the breast, ovary, pancreas or prostate." (PMID 34750509, 2021). "In addition to the BRCA1 and BRCA2 genes, there are other susceptibility genes reported to date as high penetrance and moderate penetrance genes involving in the development of breast cancer." (PMID 34045478, 2021). "Heterozygous pathogenic germline variants in PALB2 have been associated with an increased risk of breast cancer which approaches that seen with variants in BRCA2, in the order of 48–63%, with increased risks for those patients with a family history of breast cancer." (PMID 34771713, 2021). "Therefore, in this study, we aimed to evaluate the risk assessment for BRCA1- and BRCA2- associated breast cancer using fuzzy logic and neural networks systems." (PMID 34828379, 2021). "However, the lifetime risk of breast cancer is significantly higher in men with BRCA1 or BRCA2 mutation, with a incidence of 1.2% in men who carry a BRCA1 mutation and 6.8% in men who carry a BRCA2 mutation." (PMID 34711195, 2021).